CLU (clusterin)
Diseases named in the same sentence as CLU in open-access papers (continued):
Sharing a sentence is not in itself a finding about the gene and the disease.
endometriosis (3 papers, 2021 to 2024). The growth of functional endometrial tissue in anatomic sites outside the uterine body. "Therefore, we propose that the decreased levels of MT1-MMP in cases with endometriosis using contraception could be caused by contraceptives, possibly by reducing the thickness of the endometrium, resulting in reduced clusterin levels." (PMID 37893104, 2023). "In the past, we have shown that contraceptives, especially dienogest alone or together with ethinylestradiol, reduced clusterin levels in the endocervical mucus of cases with endometriosis." (PMID 37893104, 2023). "In addition, some identified hub genes of the EC (TAGLN, GATA6, CDH3, CLU, COL8A1, MYH11, MYOCD) and EU (CXCL13, DDK-1, KLF4, CYP2E1, CYP4B1 and PROK1) have been reported be associated with endometriosis." (PMID 34522169, 2021).
epilepsy (3 papers, 2016 to 2025). A brain disorder characterized by episodes of abnormally increased neuronal discharge resulting in transient episodes of sensory or motor neurological dysfunction, or psychic dysfunction. "Still, several epilepsy studies have shown a 20–30% reduction in serum clusterin levels in patient with “idiopathic temporal lobe epilepsy” or “idiopathic epilepsy”27,28." (PMID 31882899, 2019). "In humans, CSF analysis of clusterin typically revealed a 20–80% reduction in drug-responsive and drug-refractory epilepsy patients with temporal lobe epilepsy compared with controls." (PMID 31882899, 2019). "In patients and in animal model studies of epilepsy and TBI, as well as in the present experimental TBI study, the match in clusterin levels between different tissues is less apparent." (PMID 31882899, 2019). "So far, none of the previous studies has analysed clusterin as a biomarker for post-traumatic epilepsy." (PMID 31882899, 2019). "Our preliminary analysis, which was powered to detect significance if the AUC was 0.900 or higher did not support the idea that plasma clusterin would differentiate rats with or without post-traumatic epilepsy." (PMID 31882899, 2019).
esophageal cancer (3 papers, 2014 to 2021). A primary or metastatic malignant neoplasm involving the esophagus. "The decreased expression of CLU has also been reported in non-small-cell lung cancer, testicular seminoma, prostate, and esophageal cancers." (PMID 34178453, 2021). "In particular, the expression level of two proteins, periplakin and clusterin, were nearly zero in esophageal cancers when compared to healthy tissue." (PMID 27053248, 2016). "We may be able to use periplakin and clusterin to assess changes in patients with esophageal cancers." (PMID 27053248, 2016).
glomerulonephritis (3 papers, 2020 to 2023). A renal disorder characterized by damage in the glomeruli. "It has also been shown that U-FABP4 is increased before an increase in serum creatinine, clusterin or cystatin C in a drug-induced glomerulonephritis model with N-phenylanthranilic acid and puromycin in in vivo and in vitro studies." (PMID 33143633, 2020). "Compared with the normal rats, the anti-GBM mAb–induced glomerulonephritis rats showed progressive elevation of the kidney injury molecule-1 (KIM-1), β2 microglobulin, and clusterin levels in the urine as well as IFN-γ expression in the kidneys." (PMID 33159802, 2021).
heart failure (3 papers, 2019 to 2025). Inability of the heart to pump blood at an adequate rate to meet tissue metabolic requirements. "A recent study showed that lower serum clusterin was associated with higher rates of mortality in heart failure patients, indicating some uncertainty on the importance of circulating clusterin in the CVD process." (PMID 33717095, 2021).
kidney injury (3 papers, 2020 to 2025). Trauma to the kidney. "Urine samples were collected and six urine biomarkers (calbindin, clusterin, GST-π, IL-18, KIM-1, MCP-1) associated with kidney injury were assessed using the Bio-Plex Pro RBM Human Kidney Toxicity Assays kit (Bio-Plex Manager software 4.0)." (PMID 40650014, 2025). "Calbindin 1, clusterin, GSTP1, KIM-1, and MCP-1 concentrations in maternal plasma could be used in the monitoring of kidney injury in preeclamptic women; however, there is a need to perform longitudinal studies." (PMID 40649927, 2025).
liver cirrhosis (3 papers, 2020 to 2023). "We found that the expression level of clusterin was not significantly different between the following groups: individuals above and below 55 years of age, male and female, serum Cr above and below 1.5 mg/dL, and pathological basis of chronic hepatitis and liver cirrhosis." (PMID 33381244, 2020).
malaria (3 papers, 2011 to 2020). Malaria is a serious and sometimes fatal disease caused by a parasite that commonly infects a certain type of mosquito which feeds on humans. "The report shows that circulatory complement-lysis inhibitor (CLI), also known as Clusterin (CLU), is highly depleted in severe malaria." (PMID 32336276, 2020). "On the other side, clusterin -also known as Apolipoprotein J- is completely absent from the sera of malaria patients." (PMID 22028888, 2011). "The function of clusterin in the context of malaria diseases is not yet clear." (PMID 22028888, 2011).
memory impairment (3 papers, 2018 to 2024). "For example, the microglia AD genes, including APP, CLU, BACE2, and BIN1, are specifically enriched for other diseases such as neurofibrillary degeneration, Parkinson’s dementia, and aging memory impairment." (PMID 34044854, 2021).
metastatic carcinoma (3 papers, 2011 to 2022). A carcinoma which has spread from the original site of growth to another anatomic site. "Moreover, the overexpression of CLU in bone-metastatic cancer cells not only apparently inhibited the invasion and migration of these bone-metastatic cancer cells, but also decreased the phosphorylation of ERK1/2 without affecting ROCK1 expression levels." (PMID 35626071, 2022).
myopia (3 papers, 2019 to 2022). "Interestingly, rs11136000 from CLU is also strongly associated with multiple eye phenotypes (nearsightedness, myopia, glasses, astigmatism)." (PMID 33152005, 2020). "eQTLs at PARP12 and CLU colocalized with AMD and myopia signals, respectively, under both conditions." (PMID 31123710, 2019).
non-small cell lung carcinoma (3 papers, 2017 to 2022). A group of at least three distinct histological types of lung cancer, including non-small cell squamous cell carcinoma, adenocarcinoma, and large cell carcinoma. "In terms of the relationship between CLU and cisplatin resistance, it has been found that CLU silencing could promote the anti-tumor activity of cisplatin in human non-small cell lung cancer xenografts." (PMID 35687899, 2022).
Onset (3 papers, 2015 to 2021). The age group in which disease manifestations appear. "The notion that dysregulation of the complement system occurs upstream rather than downstream of an inherent neurodegenerative process is supported by the observation that genetic variability in both Clusterin and CR1 is associated to risk of late-onset AD." (PMID 26502875, 2015). "Through genome-wide association studies and other methods, it has been found that many genes related to lipid metabolism, immune response, and endocytosis are correlated with the occurrence of late-onset AD, including APOE, TREM2, PICALM, and CLU." (PMID 33806413, 2021).
papillary thyroid cancer (3 papers, 2015 to 2025). "We found that APOE and CLU were the hub genes regulating proliferation and invasion through the extracellular matrix in papillary thyroid cancer." (PMID 33521130, 2021). "Immunohistochemical analysis showed an overall up-regulation of CLU protein expression in papillary carcinoma." (PMID 25934174, 2015). "The immunohistochemical analyses showed an overall CLU up-regulation in papillary carcinoma." (PMID 25934174, 2015). "Surprisingly, CLU and APOE expression showed strong relationships with the prognosis of patients with papillary thyroid cancer." (PMID 33521130, 2021). "CLU and APOE are involved in the molecular mechanism of papillary thyroid cancer." (PMID 33521130, 2021).
prion disease (3 papers, 2010 to 2023). A transmissible disease that is caused by a protein that is able to induce abnormal folding of normal cellular proteins, leading to characteristic spongiform brain changes, which are associated with neuronal loss without an inflammatory response. "Clusterin (Clu) was considered to be of particular interest as it has already been implicated in prion disease." (PMID 21151910, 2010). "In the context of prion disease, Clusterin shows an ability to bind misfolded protein with high avidity, and it has been shown to reduce the cytotoxicity of amyloid-β in AD." (PMID 24366862, 2014). "Thus, using a commercially available sandwich immunoassay, we examined the utility of Clusterin as a candidate serum biomarker for prion disease." (PMID 24366862, 2014). "This shows that serum Clusterin estimates are unsuitable as a biomarker for prion disease." (PMID 24366862, 2014). "Data showing that a clusterin knockout mouse inoculated with BSE prions has a significantly increased incubation time suggested that Clu was a particularly good candidate quantitative trait gene for prion disease incubation time." (PMID 21151910, 2010). "Although Picalm and Cr1 have not previously been implicated in prion disease there is ample evidence to suggest that clusterin may be involved." (PMID 21151910, 2010). "Although previous data clearly implicates clusterin in prion disease, our data show that it does not contribute to the natural variation observed in the RML model of mouse incubation time." (PMID 21151910, 2010).
retinal degeneration (3 papers, 2016 to 2020). Degeneration of the retina. "The up-regulation of clusterin was reported in the animal models of retinal degeneration such as rds/rds mouse and light-induced damage in which photoreceptor death occurs by apoptosis." (PMID 28767729, 2017). "Clusterin is a chaperone protein that protects cells and is involved in various pathophysiological stresses, including retinal degeneration." (PMID 28767729, 2017). "Interestingly, clusterin expression is increased in light-induced retinal degeneration." (PMID 27893831, 2016).
retinitis pigmentosa (3 papers, 2017 to 2023). Retinitis pigmentosa (RP) is an inherited retinal dystrophy leading to progressive loss of the photoreceptors and retinal pigment epithelium and resulting in blindness usually after several decades. "Based on CLU’s cytoprotective role in retinal degenerative diseases, the relationship between CLU and retinitis pigmentosa (RP) has been studied in recent years." (PMID 37685987, 2023).
serous ovarian cancer (3 papers, 2009 to 2014). "On the contrary, it was reported that high expression of CLU was related to favorable prognosis in advanced-stage (stage III) serous ovarian cancer." (PMID 22185350, 2011). "Even though we did not detect any differences in relation to survival in our analysis, the expression of CLU, CAPG, and PRAME might still be associated with the development and progression of serous ovarian adenocarcinomas." (PMID 19775429, 2009). "In this study, we performed an external validation of four potential prognostic biomarkers, ITGB3, CLU, CAPG, and PRAME, in advanced ovarian serous adenocarcinomas." (PMID 19775429, 2009). "Prominent among these genes were those encoding platelet derived growth factor receptor alpha (PDGFRα), vascular cell adhesion molecule (VCAM), clusterin, intercellular adhesion molecule 1 (ICAM-1), and serine/threonine phosphatase 1 (Wip1), which are overexpressed in human serous ovarian cancer." (PMID 24603706, 2014).
type 1 diabetes mellitus (3 papers, 2016 to 2024). A chronic condition characterized by minimal or absent production of insulin by the pancreas. "Next, we used immunohistochemistry to measure clusterin protein in the glomeruli of mice with STZ-induced type 1 diabetes and age-matched control mice." (PMID 32913257, 2020). "To support our findings in patients with DN, we also measured glomerular clusterin protein expression in a mouse model of type 1 diabetes and observed increased glomerular clusterin protein expression in mice with STZ-induced type 1 diabetes compared to control mice." (PMID 32913257, 2020).
adenoma (2 papers, 2011 to 2015). A neoplasm arising from the epithelium. "However, these adenomas all expressed p16, and >90% abundantly expressed cytoplasmic clusterin associated with induction of the Cdk inhibitor p15 in 70% of gonadotroph and in 26% of somatotroph lineage adenomas (p = 0.006)." (PMID 21464964, 2011). "Murine LβT2 and αT3 gonadotroph pituitary cells, and αGSU.PTTG transgenic mice with targeted gonadotroph cell adenomas also abundantly expressed clusterin and exhibited features of oncogene-induced senescence as evidenced by C/EBPβ and C/EBPδ induction." (PMID 21464964, 2011). "Only 1 of 17 GH/PRL-secreting adenomas (6%) expressed high clusterin levels, 3 expressed moderate levels, while this protein was minimally detectable in 13 such adenomas." (PMID 21464964, 2011). "In contrast, clusterin strongly co-localized with αGSU in all 3 gonadotroph cell adenomas analyzed." (PMID 21464964, 2011). "Three different adenoma types (GH-, PRL- and gonadotroph) were each analyzed for co-localization of clusterin with respective pituitary hormone markers." (PMID 21464964, 2011). "In contrast, 33 of 36 (92%) of the more commonly encountered non-functioning adenomas exhibited abundant clusterin cytoplasmic immunopositivity." (PMID 21464964, 2011).
age-related hearing loss (2 papers, 2021 to 2025). "In this study, we reported the protective effect of Clusterin deficiency against age-related hearing loss and drug-induced ototoxicity, which are both due to irreversible loss of sensory HCs and degeneration of the spiral ganglion neurons (SGNs)." (PMID 34194490, 2021).
alcohol dependence (2 papers, 2020 to 2023). Physical and psychological dependence on alcohol. "Other salivary glycoproteins, such as α-amylase, clusterin, haptoglobin, and light and heavy chain immunoglobulin, identified as potential markers of alcohol dependence need further direct research, based on a larger sample." (PMID 33334005, 2020).
allergic rhinitis (2 papers, 2020 to 2025). Inflammation of the nasal mucous membranes caused by an IgE-mediated response to external allergens. "Notably, APOA1, APOA2, APOE, and clusterin (ApoJ) are selectively elevated in allergic rhinitis, where they might contribute to lipid transport and have anti-inflammatory functions." (PMID 41369347, 2025).
Anxiety (2 papers, 2020 to 2025). Intense feelings of nervousness, tension, or panic often arise in response to interpersonal stresses. "However, CLU KO-TauP301L mice had increased anxiety-like behavior, measured by the time spent in a center of the open field arena, compared to CLU WT-TauP301L." (PMID 33261653, 2020).
autoimmune myocarditis (2 papers, 2014 to 2019). Autoimmune myocarditis is an autoimmune disease that affects the heart. "The severity of autoimmune myocarditis was increased in CLU-deficient mice, and inflammation progressed rapidly." (PMID 24803721, 2014). "In vivo CLU has anti-inflammatory functions; indeed, in the experimental model of induced autoimmune myocarditis and pancreatitis, CLU knockout mice (CLUKO) show signs of more severe inflammation and cellular pathology than CLU-expressing wild-type controls (WT)." (PMID 31885575, 2019).
Autoimmunity (2 papers, 2016 to 2020). The occurrence of an immune reaction against the organism's own cells or tissues. "In a model of apoptotic cell-induced autoimmunity, and relative to control mice, CLU knockout mice developed symptoms of autoimmunity, including the generation of anti-dsDNA antibodies, deposition of immunoglobulins and complement components within kidneys, and splenomegaly." (PMID 33374364, 2020).
cerebrovascular disease (2 papers, 2016 to 2023). "One possible explanation is that the body responds to stressors, such as phosphorylated tau protein aggregation or cerebrovascular disease induction, by increasing clusterin concentration." (PMID 37941999, 2023). "We assessed the distribution of clusterin immunoreactivity in cerebrovascular disorders, particularly focusing on white matter changes in small vessel diseases." (PMID 25940137, 2016).
Cholestatic liver disease (2 papers, 2020 to 2025). "The present study demonstrated that clusterin deficiency promotes cholestatic liver disease by inducing ER stress and NLRP3 inflammasome activation and that clusterin inhibits ER stress-induced NLRP3 inflammasome activation." (PMID 40089787, 2025). "Next, to determine the effect of clusterin on cholestatic liver disease, clusterin-KO mice were fed a DDC diet for 10 or 20 days." (PMID 40089787, 2025). "First, we investigated whether the expression level of clusterin is altered in cholestatic liver disease model." (PMID 40089787, 2025). "We also reported that clusterin expression is increased in a BDL model, and liver damage was significantly more pronounced in clusterin-KO mice subjected to BDL, highlighting the important protective role of clusterin in cholestatic liver disease characterized by severe fibrosis." (PMID 40089787, 2025).
chronic hepatitis (2 papers, 2018 to 2020). An active inflammatory process affecting the liver for more than six months. "Similarly, nonviral etiologies, LPS/D-GaIN-induced ALF, and chronic hepatitis cases could be justified by protein aggregates mediated by vitronectin or clusterin (complement regulatory proteins), limited to the measurement of the complement components." (PMID 30402508, 2018).
chronic kidney disease (2 papers, 2017 to 2026). Impairment of the renal function secondary to chronic kidney damage persisting for three or more months. "Urinary epidermal growth factor (uEGF) and clusterin (uCLU) are emerging biomarkers in chronic kidney disease (CKD), but rigorous analytical validation is required before clinical implementation." (PMID 42123423, 2026).
colitis (2 papers, 2023 to 2024). Inflammation of the colon. "In summary, clusterin deficiency relieved psoriatic skin inflammation and colitis induced by long-term topical administration of IMQ." (PMID 37717073, 2023). "Long-term administration of IMQ induced systemic inflammation and colitis; however, both were alleviated by the genetic deletion of clusterin." (PMID 37717073, 2023). "Here, we found that clusterin facilitates systemic inflammation and colitis, indicating that its effects are not limited to local skin inflammation." (PMID 37717073, 2023).
colorectal tumors (2 papers, 2007 to 2024). "It has previously been reported that only one of these variants, CLU35, was down-regulated in human colorectal tumors samples compared to normal tissue indicating that the CLU mRNA variants may be differentially regulated." (PMID 17634137, 2007). "A RevSC signature, that includes CLU, has been confirmed in human colorectal tumours and, similarly to what has been observed in the mouse intestine, it appears to be largely mutually exclusive with the LGR5+ve stem cell signature." (PMID 38319453, 2024).
cyst (2 papers, 2016 to 2021). A sac-like closed membranous structure that may be empty or contain fluid or amorphous material. "Such comparison resulted in 4 upregulated (CP, CEACAM5, DMBT1, and KRT6A) and 8 downregulated (CEL, CPA1, CPB1, ALB, SERPINA4, CA2, CLU, and AMBP) DEGs secreted in cyst fluid of high-risk IPMNs." (PMID 34790815, 2021). "Clusterin is strongly induced in the cystic proximal tubule of the (cy/+) rat, but is also massively upregulated in distal tubular segments, including also non-cystic tubules during cyst development and fibrosis." (PMID 27231899, 2016).